AQP8 (aquaporin 8)
Diseases named in the same sentence as AQP8 in open-access papers (continued):
Sharing a sentence is not in itself a finding about the gene and the disease.
esophageal cancer (2 papers, 2022 to 2023). A primary or metastatic malignant neoplasm involving the esophagus. "As a member of the AQPs, AQP8 has attracted attention because of its involvement in the development of many tumors, including ovarian and esophageal carcinomas." (PMID 37280594, 2023).
liver disease (2 papers, 2024 to 2026). "Given its localization and solute transport capabilities, we hypothesized that AQP8 facilitates AcH excretion into bile, which could, in turn, influence alcohol drinking behavior and the progression of alcohol-associated liver disease (ALD)." (PMID 41522337, 2026). "Furthermore, chronic alcohol exposure downregulated hepatic Aqp8 expression, whereas overexpression of hepatic Aqp8 alleviated dysregulated lipid metabolism and liver inflammation in a murine model of alcohol-associated liver disease (ALD)." (PMID 41522337, 2026).
Malignant Melanoma (2 papers, 2010 to 2023). "The putative involvement of aquaporins in the progression of melanoma, uncovered by our method in our results, warrants further investigation as it has been recently shown that another member of this family (AQP8) also facilitates hydrogen peroxide diffusion across membranes." (PMID 20805891, 2010).
Polyhydramnios (2 papers, 2017 to 2020). The presence of excess amniotic fluid in the uterus during pregnancy. "In polyhydramnios cases, the expression of AQP8 in the amnion and that of AQP9 in the amnion and the chorion were significantly increased in the idiopathic polyhydramnios group; however, their expression in the placenta was significantly decreased." (PMID 29194396, 2017). "Hence, upregulation of AQP8 in the foetal membranes after AQP1 depletion may lead to polyhydramnios through a compensatory mechanism, while the expression of AQP9 in the placenta and foetal membranes is decreased after AQP1 depletion." (PMID 32542408, 2020).
primary Sjögren's syndrome (2 papers, 2019 to 2021). "However, some Fezf2-dependent TRAs identified in mice are autoantigens in humans, including aquaporin 8 (AQP8) in Sjögren syndrome and transthyretin (TTR) in juvenile idiopathic arthritis (JIA)." (PMID 33537838, 2021). "In addition AQP8 was the major antibody target on human salivary glands in patients with primary Sjögren's syndrome." (PMID 30863397, 2019).
steatosis (2 papers, 2022 to 2026). Increased lipid within the cytoplasm of cells. "Collectively, these findings demonstrate that chronic alcohol consumption impairs hepatic AQP8, which highly contributes to impaired bile flow and exacerbates liver inflammation, steatosis, and oxidative stress in the context of ALD." (PMID 41522337, 2026).
adenocarcinoma of the colon (1 paper, 2023). "For example, recent studies using immunohistochemistry showed that AQP8 expression was low in adenocarcinoma of the colon and higher levels of AQP8 were significantly associated with better survival in CRC patients." (PMID 37296884, 2023).
cholelithiasis (1 paper, 2024). The presence of crystallized deposits forming in the gallbladder or biliary tree, primarily composed of cholesterol, bilirubin, and bile. "Interestingly, in Aqp8+/+ wild-type mice, scutellarin significantly increased bile formation, reduced bile lipid concentrations, and prevented cholelithiasis compared to Aqp8−/− knockout mouse littermates." (PMID 39596202, 2024).
cholera (1 paper, 2010). "Furthermore, observations in rat intestine verify down regulation of AQP8 following CTX exposure (conversely, AQP10 is down regulated in human cholera patients)." (PMID 22069677, 2010). "However, results in a recent AQP8 (−/−) model do not support the hypothesis that AQP8 serves as an important route for water secretion in cholera, as the affected mice showed a normal secretory response to CTX." (PMID 22069677, 2010).
collagenous colitis (1 paper, 2022). A type of microscopic colitis of unknown etiology. "In a previous study, AQP8 was found to localize to the apical membrane of the colonic intestinal epithelial cells (IECs), and down-regulation of epithelial AQP8 may impair water resorption in active collagenous colitis (CC), resulting in watery diarrhea." (PMID 35880566, 2022).
Diarrhea (1 paper, 2023). Abnormally increased frequency (usually defined as three or more) loose or watery bowel movements a day. "Diarrhea is commonly associated with abnormal water metabolism in the intestine, which is regulated by AQP3, AQP4, and AQP8 proteins." (PMID 37237988, 2023).
endometriosis (1 paper, 2020). The growth of functional endometrial tissue in anatomic sites outside the uterine body. "AQP8 is overexpressed in eutopic endometrial cells of women with endometriosis." (PMID 33321760, 2020).
endotoxemia (1 paper, 2018). "In an endotoxemia rat model hepatic mitochondrial Aqp8 expression is reduced." (PMID 29449936, 2018). "Regulation of Aqp8 in endotoxemia and septic models by substances like tetramethylpyrazine or ethyl pyruvate could stabilize the mitochondria membrane potential, protect hepatocellular mitochondria from damage and might therefore be a therapeutic option in sepsis." (PMID 29449936, 2018).
enteritis (1 paper, 2016). Inflammation of the small intestine. "On the other hand, the downregulated expression of several AQPs (AQP1, AQP3, AQP4, AQP7, AQP8, AQP10 and AQP11) in the small and large intestines has been observed in the process of either enteritis or diarrhea." (PMID 27589719, 2016).
extrahepatic cholestasis (1 paper, 2019). Impairment of the bile flow caused by an obstruction in the portion of the bile duct system located outside of the liver. "Regardless the causes involved, a differential degradation status may explain why AE2 is responsive to cAMP in hepatocytes from animals with extrahepatic cholestasis, but AQP8 is not." (PMID 30789925, 2019).
gallbladder inflammation (1 paper, 2021). "They reported about the expression of AQP8 in the gallbladder mucosa of humans with small pigment stones without gallbladder inflammation and with similar bile composition as in healthy humans." (PMID 34650971, 2021).
gastric cancer (1 paper, 2018). A primary or metastatic malignant neoplasm involving the stomach. "In addition, elevated expression of AQP8 mRNA in all gastric cancer patients was associated with poor OS, prominently in both male and female intestinal type gastric cancer patients, and similarly in stages I and III patients." (PMID 29678898, 2018). "Similarly, high expression of AQP3 and AQP9 mRNA revealed improved OS in female patients, whereas AQP0, AQP1, AQP6/2L and AQP8 were associated with poor OS in gastric cancer." (PMID 29678898, 2018). "Nonetheless, AQP0, AQP6, and AQP8 mRNA expression with surgery alone and AQP9 mRNA with 5 FU chemotherapy were associated with significantly increased risk of low survival rate in gastric cancer patients." (PMID 29678898, 2018). "In the present study, we documented that high mRNA level of AQP0, AQP4, AQP2L/6, and AQP8 were associated with worse OS in either HER2 positive or HER2 negative gastric cancer patients." (PMID 29678898, 2018). "In which, we revealed AQP3, AQP9, and AQP11 mRNA expression were associated with improved OS in all gastric cancer patients especially with intestinal subtypes, whereas AQP0, AQP1, AQP4, AQP5, AQP6/2L AQP8, and AQP10 mRNA expression were associated with poor OS in all gastric cancer patients." (PMID 29678898, 2018). "Furthermore, AQP8 and AQP11 mRNA expression in other adjuvant chemotherapy showed better OS in gastric cancer patients." (PMID 29678898, 2018).
gastric tumor (1 paper, 2018). "However, AQP1 and AQP8 showed a trend toward decreased expression in normal gastric tissues, whereas its high and medium expression was documented respectively in cytoplasmic and membranous region of gastric tumor tissues." (PMID 29678898, 2018).
Hyperammonemia (1 paper, 2018). An increased concentration of ammonia in the blood. "Ammonia translocates into the inner mitochondrial membrane via aquaporin-8 mitochondrial channels, which are down-regulated in lipopolysaccharide-treated animal models, leading to impaired ureagenesis and causing hyperammonemia." (PMID 30049989, 2018).
hyperlipidemia (1 paper, 2022). "aqp8 knockout mice had no profound liver dysfunction but were reported to develop mild hyperlipidemia, consistent with the hyperlipidemia observed in cholestasis patients with decreased or obstructed bile flow." (PMID 35163313, 2022).
irritable bowel syndrome (1 paper, 2024). Irritable bowel syndrome (IBS) is a chronic functional condition of the lower gastrointestinal (GI) tract characterized by abdominal pain or discomfort and disordered bowel habit (diarrhea, constipation, or fluctuation between the two). "Given the immune responses and inflammation associated with irritable bowel syndrome (IBS), our hypothesis focuses on the LPS-activated NF-κB pathway in our cellular model, highlighting its pivotal role in regulating AQP8 expression in the context of IBS." (PMID 38612611, 2024).
Obesity (1 paper, 2021). Accumulation of substantial excess body fat. "Importantly, the expression levels of intestinal secretory and absorptive genes (aqp8 and muc2.1), and obesity-related genes (fgf2 and pomca) were significantly up-regulated in the DEHP exposed groups." (PMID 34675901, 2021). "The crucial genes of aquaporin 8a (aqp8), mucin 2.1 (muc2.1), fibroblast growth factor 2 (fgf2), and proopiomelanocortin a (pomca) can indicate the intestinal secretory and absorptive-, and obesity-related functional abnormality in the host." (PMID 34675901, 2021).
ovarian insufficiency (1 paper, 2022). "AQP8 might be a potential target for diseases related to ovarian insufficiency." (PMID 36081911, 2022).
pancreatic cancer (1 paper, 2025). "For that, we cultured a pancreatic cancer cell line, BxPC3, that was screened for AQP expression, revealing high levels of AQP3 and AQP5 expression and much lower levels of AQP1 and AQP8." (PMID 40305202, 2025).
pancreatitis (1 paper, 2023). Inflammation of the pancreas. "A study on pancreatitis suggested that the RIPK1/NF-κB/AQP8 axis may inhibit acinar cell necrosis." (PMID 37378023, 2023).
skin aging (1 paper, 2024). The gradual irreversible changes in structure of skin that occur as a result of the passage of time.. "This discovery of AQP8’s protective effect on human dermal fibroblasts is significant since it may pave the way for developing novel strategies to prevent or reduce skin aging by targeting AQP8 activity." (PMID 38465340, 2024).
small intestinal disease (1 paper, 2021). "In our experiment, NSAID-induced small intestinal disease model rats intervened by berberine showed significantly change in HTR4, F2RL3, NPY, CRHR2, IL1b, VIP, AQP8, NOS1." (PMID 34284820, 2021).
type 2 diabetes (1 paper, 2015). "Whether or not AQP8 is (i) co-regulated with the proteins in mitochondrial respiration, (ii) related to the specific function in adipocytes, and (iii) involved to pathological changes of adipocytes in type 2 diabetes." (PMID 29124204, 2015).
viral infection (1 paper, 2022). "Our results indicated that cryopreservation did not significantly alter the viral infection efficiency, but influenced AQP8 expression in the infected cells at both protein and mRNA levels compared with the non-cryopreserved samples." (PMID 35245307, 2022). "However, WB and RT-qPCR results obtained during the assessment of viral infection showed that, in stably infected cells without cryopreservation, the expression of AQP8 was inhibited at both mRNA and protein levels; this was consistent with our expectation." (PMID 35245307, 2022).
cancer (16 papers, 2010 to 2024). A tumor composed of atypical neoplastic, often pleomorphic cells that invade other tissues. "Another important member of the AQP family, AQP8, is more frequently investigated in cancers of the reproductive and digestive systems, and less in those of the nervous system." (PMID 37280594, 2023). "Low levels of AQP8, which only enriched in apical part of the cell, have revealed to significantly promotes cancer growth and metastasis." (PMID 35907803, 2022). "For example, AQP8 showed various expression patterns in diverse tissues, suggesting specific roles for AQP8 in different cancers." (PMID 32457800, 2020). "Knocking out one specific aquaporin, AQP8, significantly weakens the anti-cancer capacity of PSM on U87MG cells." (PMID 28667316, 2017). "It has been reported that AQP8 in cancer cells is involved in cell migration via the EGFR pathway." (PMID 32260143, 2020). "Furthermore, a role for AQP8 has been described in many human cancer cell lines." (PMID 30893772, 2019). "Similar results have been reported on the reduced proliferation of cancer cell lines by silencing the peroxiporins AQP3, AQP5, and AQP8." (PMID 35741021, 2022). "Aquaporin-8 can modulate the transport of hydrogen peroxide produced by NAD(P)H oxidase in leukemia cells, suggesting novel targets for cancer therapy in that, in general, cancer cells are under persistent oxidative stress." (PMID 25221514, 2014). "Overall, several AQPs, including AQP1, AQP3, AQP4, AQP5, AQP8, and AQP9, have been suggested to transport H2O2, and their expression promotes cancer cell growth and migration, However, solid data exist only for AQP3- mediated H2O2 transport as one of the key mechanisms for cancer cell migration." (PMID 35847914, 2022).
tumor (16 papers, 2009 to 2026). "Compared with normal controls, the relative mRNA expression levels of NOX4, SCD, and TIMP1 were significantly higher in tumor tissues, while those of AQP8 and NR5A2 were significantly lower." (PMID 41438584, 2026). "The available evidence suggests that AQP8 plays a role in tumorigenesis, specifically in tumor cell migration, angiogenesis, and tumor growth." (PMID 41034734, 2025). "In the mouse model, compared with the control group, the AQP8 overexpression group had larger tumor volume and weight, whereas the AQP8 knockdown group had smaller tumor volume and weight." (PMID 37280594, 2023). "Tumorigenesis experiments in nude mice also showed that AQP8 overexpression enhanced tumor growth, whereas AQP8 knockdown had the opposite effect." (PMID 37280594, 2023). "In the animal experiments, the AQP8 overexpression group had higher tumor volume and weight, whereas the AQP8 knockdown group had lower tumor volume and weight compared with those parameters measured in the control group." (PMID 37280594, 2023). "According to the HPA database, the protein levels of SLC26A3, GUCA2A, CLCA4, CLCA1, and AQP8 in tumor tissues were all significantly lower than that in normal tissues." (PMID 35693937, 2022). "Notably, INHBA is a well-known tumor promoter under tumor-bearing conditions, and AQP8 is upregulated under inflammatory conditions, highlighting their potential roles in lung pathology." (PMID 40843897, 2025). "In any case, the data are suggesting that AQP8 may play different roles in different tumor types, thus warranting further research." (PMID 37280594, 2023). "The total data showed a significant increase in the expression of AQP8 in ccRCC tumor tissues." (PMID 36254092, 2022). "Recent evidence show that many tumour cell types express elevated level of aquaporin isoforms, and we previously demonstrated that aquaporin-8 acts as H2O2 transport facilitator across the plasma membrane of B1647 cells, a model of acute myeloid human leukemia." (PMID 30581529, 2018). "Additionally, knocking down Ndrg1 in BLM tumor organoids reduced secretory progenitor marker gene expression (Sox4, Atoh1, Dll1, Notch1), but increased enterocyte marker gene expression (Cdhr2, Aqp8)." (PMID 38893159, 2024). "AQP8 can inhibit the growth of tumor cells, and CRC patients with high levels of AQP8 have a better survival time." (PMID 34778915, 2021). "CD177 and AQP8 were downregulated in all 79 CRCs while GPX3, a “tumor suppressor”, was downregulated in 75 out of 79 CRCs (log2T/N < 0)." (PMID 31409279, 2019). "Gelatinase activity was one major GO annotation of these eight genes (CA7, SPIB, GUCA2B, AQP8, IL6R, SPP1, TCN1, and CWH4) and is related to tumor progress and metastasis." (PMID 24959000, 2014). "AQP8 modulates ROS levels within the TME, influencing immune cell behavior and promoting the recruitment of suppressive cells like Regulatory T cells (Tregs) and MDSCs, which create an immunosuppressive environment that supports tumor progression." (PMID 39610918, 2024). "All 3 oncogenes in 50 CRCs, except for MYC in one tumor and CDK4 in three tumors, were upregulated and 3 normal colonic physiological genes were downregulated, except for CD177 in one tumor, AQP8 in two tumors and GPX3 in three tumors." (PMID 31409279, 2019). "The results showed that the AQP8 is mostly expressed in tumor tissues rather than normal tissues." (PMID 37280594, 2023). "According to the GEPIA database, AQP1, AQP3, AQP4, and AQP9 were significantly expressed in LUAD tissues compared to normal lung tissues (p < 0.05), but some genes including AQP0, AQP5, AQP6, AQP7, AQP8, AQP10, and AQP11 were not differentially expressed between tumor and normal tissues." (PMID 34708074, 2021).
infection (4 papers, 2013 to 2023). The state of being infected such as from the introduction of a foreign agent such as serum, vaccine, antigenic substance or organism. "The most downregulated gene was that coding for aquaporin 8 with a downregulation as low as 97 fold observed 5 days post-infection." (PMID 23687968, 2013). "AQP8 can regulate ROS production in Botrytis cinerea, which in turn affects its infection ability." (PMID 36321895, 2022).
bacterial infection (1 paper, 2020). "However, under stress and bacterial infection (e.g., Fusobacterium) conditions, AQP1, AQP3, AQP8, and AQP10 are mainly responsible for the maintaining of water homeostasis in the gastrointestinal tract." (PMID 32565721, 2020).
colonitis (1 paper, 2022). "In the murine colonitis model, the expression level of AQP8 is reversely correlated with the occurrence of inflammation and injury." (PMID 35880566, 2022).
gastrointestinal disease (1 paper, 2019). A disease that occurs in the gastrointestinal system, excluding the hepatobiliary system. "Currently several researches reported that AQP8 play important roles in gastrointestinal diseases, including UC." (PMID 31741804, 2019).
gastrointestinal disorders (1 paper, 2024). "The existing literature emphasizes AQP8’s significant role in functional gastrointestinal disorders." (PMID 38612611, 2024).
inflammation (1 paper, 2024). Aberrant reaction of the microcirculation characterized by movement of fluid and leukocytes from the blood into extravascular tissues. "Moreover, AQP8 may be used as a resistance gene against Salmonella enterica infection, intestinal inflammation, and other related diseases in pigs." (PMID 38473174, 2024).
AQP8 also shares sentences with these, for which no sentence is quoted: Crohn disease (5 papers); acute pancreatitis (2); intestinal diseases (2); acute myeloid leukemia (1); adenocarcinoma (1); endometrial cancer (1); Epididymis (1); gestational diabetes mellitus (1); Hepatic steatosis (1); Infertility (1); juvenile idiopathic arthritis (1); liver cancer (1); liver fibrosis (1); malignant epithelial ovarian tumors (1); metabolic disorders (1); nephrogenic diabetes insipidus (1); papillary renal cell carcinoma (1); pleural mesothelioma (1); rectal adenocarcinoma (1); renal carcinoma (1); renal pelvis urothelial carcinoma (1); Sepsis (1); thyroid carcinoma (1); type 1 diabetes mellitus (1).